MMP8 (matrix metallopeptidase 8)
Diseases named in the same sentence as MMP8 in open-access papers (continued):
Sharing a sentence is not in itself a finding about the gene and the disease.
acute peritonitis (4 papers, 2010 to 2025). "The accumulation of macrophages in the peritoneal cavities of mice during thioglycollate‐induced peritonitis was compared in WT and Mmp‐8−/− mice." (PMID 33656791, 2021). "Peritoneal macrophage accumulation was similar in WT and Mmp‐8−/− mice with sterile acute peritonitis." (PMID 33656791, 2021). "Similar to our results, increased MMP-8 levels have also been observed in a study with peritonitis patients, the majority of who had septic shock." (PMID 20356362, 2010). "Patients experiencing technique failure after an episode of acute peritonitis had marginally higher levels of calprotectin, MMP-8, sIL-6R, and transforming growth factor-β in their dialysis effluent as well as lower CD4+ : CD8+ T-cell ratios compared with uncomplicated cases." (PMID 28318629, 2017). "WT and Mmp‐8−/− mice with acute peritonitis had similar numbers of macrophages accumulating in their peritoneal cavities indicating that Mmp‐8 is not essential for macrophages to accumulate in a serosal sac, as expected." (PMID 33656791, 2021). "Mmp‐8 is not required for murine monocytes to migrate into the peritoneal cavities of mice with acute peritonitis, which is consistent with the use of proteinase‐independent amoeboid migration of monocytes." (PMID 33656791, 2021). "Herein, we show that Mmp‐8 is not required for monocytes to migrate into a serosal cavity (the peritoneum) as WT and Mmp‐8−/− mice with acute sterile peritonitis had similar numbers of macrophages accumulating in their peritoneal cavities." (PMID 33656791, 2021).
breast tumor (4 papers, 1995 to 2019). "In this study, levels of two MMPs, i.e. MMP-8 and -9, and their inhibitor tissue inhibitor of metalloprotease type 1 (TIMP-1) were measured by enzyme-linked immunosorbent assay in human breast tumours." (PMID 7734294, 1995). "Analysis of a pair of breast tumor cell lines, originating from the same breast tumor but with opposite metastatic capabilities, revealed increased expression of MMP-8 in the non-metastatic cell line and corresponding xenograft." (PMID 25848906, 2015).
chronic kidney disease (4 papers, 2019 to 2025). Impairment of the renal function secondary to chronic kidney damage persisting for three or more months. "Second, we observed that chronic renal failure was associated to significantly lower day 3 MMP-8 levels and higher day 3 TIMP-1 levels." (PMID 34043679, 2021). "Patient demographics and underlying conditions had no impact on MMP-8 or TIMP-1 levels on day 3 or 5 with the exception of chronic renal failure that was associated to lower MMP-8 (p<0.05) and higher TIMP-1 (p<0.01) values." (PMID 34043679, 2021). "Compared to chronic renal failure, the excretory system disorder pyelonephritis is not accompanied by the major impact of MMP-8 upon epithelial architectonics and function." (PMID 31881666, 2019). "Moreover, among patients with chronic renal failure MMP-8, TIMP-1 and MMP-8/TIMP-1 levels had no prognostic impact in SAB." (PMID 34043679, 2021). "However, among patients with chronic renal failure, day 3, day 5 or day 28 MMP-8, TIMP-1 or MMP-8/TIMP-1 had no significant predictive effect on mortality when analyzed by receiver operating characteristic." (PMID 34043679, 2021).
colon cancer (4 papers, 2018 to 2023). "It has been demonstrated in the colon cancer population that heightened serum MMP-8 levels are correlated with inflammatory responses and unfavorable outcomes, thus substantiating the notion." (PMID 37464428, 2023). "Among colon cancer patients, especially within those with left-sided disease, MMP-8 served as a prognostic factor." (PMID 29929486, 2018). "On the contrary, we found that high MMP-8 served as a prognostic factor in the subgroup of colon cancer and patients with tumors located on the left side of the colorectum." (PMID 29929486, 2018). "In subgroup analyses, survival was poor for patients with high MMP-8 and colon cancer (HR 2.00, 95% CI 1.10–3.64, P = 0.023), with left-sided tumor (HR 1.80, 95% CI 1.17–2.77, P = 0.007), and with no systemic inflammatory response (HR 1.66, 95% CI 1.10–2.53, P = 0.017)." (PMID 29929486, 2018). "The expression of MMP8 and MMP9, however, were not markedly changed following modulation of SREBP1, suggesting that MMP8 and MMP9 expression is not regulated by SREBP1 in colon cancer cells." (PMID 31299935, 2019).
endothelial dysfunction (4 papers, 2019 to 2025). In vascular diseases, endothelial dysfunction is a systemic pathological state of the endothelium (the inner lining of blood vessels) and can be broadly defined as an imbalance between vasodilating and vasoconstricting substances produced by (or acting on) the endothelium. "Furthermore, endothelial dysfunction is a pathogenic characteristic of preeclampsia, dysregulated MMP8 expression may play a crucial role in the disruption of angiogenesis in preeclampsia leading to endothelial dysfunction." (PMID 30976066, 2019). "MPO and its byproducts promote processes like foam cell formation, endothelial dysfunction, and MMP‐8 activation." (PMID 38852177, 2025). "As a catalytically active and tissue-destructive enzyme, MMP-8 plays a key role in progressive periodontal lesions, whereas TMAO has been implicated in endothelial dysfunction, oxidative stress, and inflammatory gene expression." (PMID 40131489, 2025).
leukemia (4 papers, 2019 to 2026). A malignant (clonal) hematologic disorder, involving hematopoietic stem cells and characterized by the presence of primitive or atypical myeloid or lymphoid cells in the bone marrow and the blood. "Analysis of gene expression in these precursor cells identified pathways that were specifically upregulated, the most pronounced of which involved matrix metalloproteinases Mmp8 and Mmp9, during leukemia progression." (PMID 38730491, 2024). "To examine the clinical relevance of the MMPs identified here, we first determined whether MMP8 and MMP9 expression is associated with clinical outcome in leukemia patients." (PMID 38730491, 2024). "Of the upregulated genes, Syne1, Atxn10 and Dach1 show activation as early as Day 11, while Ngp, Abca13, Adpgk, Mmp8 and Lcn2 were more significantly upregulated in the later stage, D14 neutrophils,which suggests a sequential activation in Camk1d + neutrophils during leukemia progression." (PMID 38730491, 2024). "Even though the leukemia data is not available in this platform, the TIMER algorithm detected a positive correlation between MMP8 expression and neutrophil infiltration in 26 of the 40 cancer types examined, most of which were validated using multiple different algorithms." (PMID 38730491, 2024).
liver cirrhosis (4 papers, 2013 to 2020). "In our previous reports using this human cDNA for MMP8 in experimental liver cirrhosis, we established a significant reduction of pro-fibrogenic genes expression, an important reduction of fibrosis index and hepatic stellate cells proliferation." (PMID 33275619, 2020). "In a rat model of liver cirrhosis, MMP-8 delivery by an adenovirus (Ad) vector achieved significant amelioration of fibrosis but application of Ad vectors in humans is subject to various issues, including a lack of intrinsic liver specificity." (PMID 23301066, 2013). "The previously observed benefits of full-length MMP-1 and MMP-8 delivery into rat models of liver cirrhosis by conventional Ad-vectors provided a standard against which the performance of our Ad-vector-shuttled HBV tMMP8 vector could be compared." (PMID 23301066, 2013). "MMP-8 levels and activity (along with MMP-2 and MMP-9) have shown to be elevated in alcoholic patients with stage C liver cirrhosis." (PMID 32414178, 2020).
meningitis (4 papers, 2010 to 2023). A disorder characterized by acute inflammation of the meninges of the brain and/or spinal cord. "In this study we showed that brain endothelial cells produced MMPs—in particular MMP-8—upon infection with Neisseria meningitidis, a bacterium that causes meningitis and septic shock." (PMID 20442866, 2010). "The mechanisms by which MMP-8 is activated during meningococcal infection will be one focus of further investigations, as delineating this process will be fundamental to increasing our understanding of the interaction between this major meningitis causing pathogen and brain endothelial cells." (PMID 20442866, 2010). "In Neisseria-induced meningitis, MMP-8 was involved in the proteolytic cleavage of the TJ protein Occludin." (PMID 31092253, 2019). "Encephalitis and meningitis patients differed with respect to other chemokines (CXCL11) and MMPs (MMP-3, MMP-8, MMP-9, and MMP-12), indicating that different location of the virus gives rise to qualitative differences in the ensuing inflammatory response." (PMID 30777092, 2019).
oral diseases (4 papers, 2021 to 2024). "The most important salivary inflammatory biomarkers linked to oral disorders include matrix metalloproteinases (MMP-8 and MMP-9), tissue inhibitors of metalloproteinase, interleukins (IL-1, IL-6, and IL-8), and tumor necrosis factor (TNF-α)." (PMID 38535833, 2024). "We recognize that other oral diseases and conditions, such as caries activity and reduced salivary flow rate, could affect MMP‐8 assays, potentially through the activation of pro‐MMP‐8 by acids produced by cariogenic bacteria." (PMID 35304757, 2022).
psoriasis (4 papers, 2016 to 2025). An autoimmune condition characterized by red, well-delineated plaques with silvery scales that are usually on the extensor surfaces and scalp. "We show a strong upregulation of MMP8 in AI lesion compared to skin from healthy controls and psoriasis patients." (PMID 27843200, 2016). "Then, chitinase-3-like protein 1 (CHI3L1) and MMP10 distinguished psoriasis from psoriatic arthritis not undergoing systemic therapy and, in the presence of onychopathy, MMP8 levels were higher in psoriasis than in psoriatic arthritis." (PMID 31717649, 2019). "Due to the lack of cutaneous MMP8 expression in psoriatic lesions, abscesses and draining sinus tracts are absent in psoriasis." (PMID 27843200, 2016). "Interestingly, increased MMP8 expression was specific for AI lesions and not observed in affected skin of patients with psoriasis, a chronic inflammatory skin disease without sinus tract development." (PMID 27843200, 2016).
pulpitis (4 papers, 2020 to 2024). Inflammation of the dental pulp. "We observed a correlation (Rho = 0.80, P < .0001) and an association (P < .0001), and high values of MMP-8 (average 1.9750 ng/mL) in the irreversible pulpitis group with responses from 6 to ≥10 seconds." (PMID 33350764, 2020). "We identified a correlation (Rho = 0.70, P < .0001) and an association (P < .0001), and high values of MMP-8 (mean = 0.3607 ng/mL) in the reversible pulpitis group with responses from 4 to 5 seconds." (PMID 33350764, 2020). "Responses to the cold test between 4 to 5 seconds (second evaluation; P < .0001) were associated with high levels of MMP-8 (mean, 0.36 ng/mL) in the reversible pulpitis group." (PMID 33350764, 2020). "The increase in seconds was associated with an increase in MMP-8 levels (Rho = 0.81, P < .0001) in teeth with pulpitis." (PMID 33350764, 2020). "We determined that an increase in the duration of response to the cold test was associated with an increase in MMP-8 levels (Rho = 0.81, P < .0001) in teeth with pulpitis." (PMID 33350764, 2020). "The aim of this study was to associate the responses to the cold test with levels of MMP-8 in teeth diagnosed with reversible and irreversible pulpitis." (PMID 33350764, 2020). "Therefore, the increase in seconds was associated with an increase in MMP-8 levels in the teeth with pulpitis." (PMID 33350764, 2020). "In pulpitis patients, MMP-8 levels were significantly higher in the GCF samples compared with the healthy group." (PMID 38947881, 2021). "In relation to the irreversible pulpitis group, we observed response frequencies during the test at 6 to ≥10 seconds with values of MMP-8 between 0.8699 and 3.9829 ng/mL." (PMID 33350764, 2020). "As in the healthy pulp group, during the first evaluation, we identified the highest response frequencies at 1 and 2 seconds in teeth with pulpitis (MMP-8 levels between 0.1000 and 0.3945 ng/mL)." (PMID 33350764, 2020). "Levels of MMP-8 and responses (in seconds) to the cold test in teeth with reversible and irreversible pulpitis." (PMID 33350764, 2020). "High values of MMP-8 were observed in the irreversible pulpitis group from 6 to ≥10 seconds (P < .0001)." (PMID 33350764, 2020). "Higher MMP-8 is included in dentin samples from reversible or irreversible pulpitis patients." (PMID 38947881, 2021). "However, during the second evaluation, the highest response frequencies were identified at 3, 4, and 5 seconds in teeth with reversible pulpitis, with values of MMP-8 between 0.0265 and 0.4917 ng/mL." (PMID 33350764, 2020). "We also compared the values of MMP-8 with the groups with responses from 1 to 5 seconds (n = 40, 20 teeth diagnosed with healthy pulps and 20 with reversible pulpitis), and the group with responses from 6 to ≥10 seconds (20 teeth diagnosed with irreversible pulpitis)." (PMID 33350764, 2020). "We compared the values of MMP-8 with the groups with responses from 1 to 3 seconds (n = 28, 20 teeth diagnosed with healthy pulps and 8 with reversible pulpitis) and the group with responses from 4 to 5 seconds (12 teeth diagnosed with reversible pulpitis)." (PMID 33350764, 2020). "We observed high values of MMP-8 in the reversible pulpitis group from 4 to 5 seconds (P < .0001)." (PMID 33350764, 2020). "Therefore, the aim of this study was to associate the responses (in seconds) to the cold test with levels of MMP-8 (in dentin samples) in teeth diagnosed with reversible and irreversible pulpitis." (PMID 33350764, 2020). "For example, when the pulp tissue of symptomatic-irreversible-pulpitis-affected teeth and GCF specimens were compared to healthy tooth pulp tissue and GCF specimens, it wa sobserved that the levels of NKA, SP, IL-8, and MMP-8 increased dramatically." (PMID 38279358, 2024).
septic shock (4 papers, 2021 to 2024). Shock caused by infection; frequently caused by gram negative bacteria, although some cases have been caused by other bacteria, viruses, fungi, and protozoa; characterized by fever, chills, tachycardia, tachypnea, and hypotension. "Higher expression levels of CD177 and MMP8 proteins were also observed in the PBMCs isolated from septic shock patients than from control participants." (PMID 37359526, 2023). "Among children with septic shock, elevated MMP8 and OLFM4 blood gene expression levels, which are markers of neutrophil activation, are associated with higher rates of mortality and organ failure." (PMID 33006196, 2021). "Quantitative Reverse Transcription Polymerase Chain Reaction validation was conducted for MMP8, MMP9, ARG1, HP, and CD163 across healthy controls, SIRS, and septic shock patient groups." (PMID 39560539, 2024). "CD177, CLEC5A, CYSTM1, MCEMP1, MMP8, and RGL4 were identified as hub genes, which were of considerable value in the early diagnosis of septic shock patients." (PMID 37359526, 2023). "In addition, higher expression levels of CD177, CLEC5A, CYSTM1, MCEMP1, MMP8, and RGL4 messenger RNA (mRNA) were observed in peripheral blood mononuclear cells (PBMCs) isolated from septic shock patients than from healthy donors." (PMID 37359526, 2023).
Shock (4 papers, 2012 to 2025). The state in which profound and widespread reduction of effective tissue perfusion leads first to reversible, and then if prolonged, to irreversible cellular injury. "Notably, members of our group are currently pursuing GZMB and MMP8 as novel therapeutic targets in septic shock, and younger age was previously linked to higher mortality in pediatric septic shock." (PMID 23025259, 2012). "For example, in pediatric septic shock, MMP8 levels were found to directly correlate with organ failure and mortality, leading to its proposal as a potential prognostic biomarker for bacterial sepsis." (PMID 41452925, 2025).
acute respiratory distress syndrome (3 papers, 2021 to 2022). Progressive and life-threatening pulmonary distress in the absence of an underlying pulmonary condition, usually following major trauma or surgery. "With its unique characteristics, MMP8 has been shown to play an important role in the pathogenesis of respiratory diseases such as acute respiratory distress syndrome or acute lung injury, COPD, interstitial lung disease, and hospital-acquired pneumonia." (PMID 35059324, 2021).
Alzheimer disease (3 papers, 2018 to 2023). A progressive, neurodegenerative disease characterized by loss of function and death of nerve cells in several areas of the brain leading to loss of cognitive function such as memory and language. "In addition, results from molecular docking studies were crucial for validating the interactions of twenty phytocompounds with high binding affinity for the target receptors AChE, COX2 and MMP8, which are involved in the physiopathology of Alzheimer’s disease." (PMID 37762197, 2023). "PANTHER pathways analysis of differentially expressed proteins revealed overrepresentation of Wnt signaling pathway (CDH1, CSNK2A2, GNA11, CTBP2, CDH17, SMARCE1, p-value 0.02), followed by Alzheimer disease-presenilin pathway (MMP8, MMP9, MLLT4, CDH1, P-value 0.04)." (PMID 29515771, 2018). "Note that the Alzheimer disease-presenilin pathway identified as the most enriched by the Panther algorithm is related to ECM remodeling (genes included in the pathway: Mmp9, Mmp8, Mmp2, Mmp13, Mmp12)." (PMID 35386010, 2022).
ankylosing spondylitis (3 papers, 2018 to 2025). An autoimmune chronic inflammatory disorder characterized by inflammation in the vertebral joints of the spine and sacroiliac joints. "We also discovered a significant positive connection between MMP8 expression and patient scores on the Bath ankylosing spondylitis functional index (BASFI)." (PMID 36221125, 2022). "A significant positive correlation between MMP8 and BASFI level (Bath Ankylosing Spondylitis Functional Index) was also seen in AS patients (P = 0.034)." (PMID 36221125, 2022).
atopic dermatitis (3 papers, 2020 to 2023). "GCF MMP-8 levels were lower in atopic dermatitis patients as compared to healthy patients." (PMID 37342498, 2023). "To conclude, this study showed that the GCF concentrations of ADAM8, ADAM9, Cathepsin E, MMP8, CD10, Protein convertase 9, and uPA/Urokinase proteases were downregulated in moderate/severe atopic dermatitis patients compared to healthy controls." (PMID 33255937, 2020).
Crohn disease (3 papers, 2020 to 2023). A gastrointestinal disorder characterized by chronic inflammation involving all layers of the intestinal wall, noncaseating granulomas affecting the intestinal wall and regional lymph nodes, and transmural fibrosis. "The most frequently analyzed metalloproteinases in Crohn’s disease are: MMP-1, MMP-3, MMP-7, MMP-8 and MMP-9." (PMID 37895443, 2023). "MMP-1, MMP-3, MMP-7, MMP-8 and MMP-9 are biomarkers of Crohn’s disease." (PMID 37895400, 2023).
diabetic foot ulcers (3 papers, 2016 to 2025). "Mechanisms could include the dampening of the pathologically excessive levels of collagenases (MMP-1 and MMP-8) and gelatinases (MMP-2 and MMP-9) that have been observed in biopsies of diabetic foot ulcers, compared to the levels of these proteinases seen in normal posttraumatic wounds." (PMID 27190999, 2016).